INS (insulin)
Diseases named in the same sentence as INS in open-access papers (continued):
Sharing a sentence is not in itself a finding about the gene and the disease.
Insulin resistance (continued). "Changes in the abundance of insulin signalling molecules in skeletal muscle and adipose tissue precede the development of insulin resistance and type 2 diabetes." (PMID 24386400, 2013). "Palmitoleic acid, segregated by adipose tissue, greatly strengthens the insulin-signaling pathway, avoiding tissue insulin resistance and obesity-related diseases." (PMID 23341976, 2013). "HOMA-IR is widely-used in epidemiologic studies as a measure of insulin resistance, and has been shown to reflect euglycemic clamp insulin resistance more accurately than fasting insulin levels alone." (PMID 23497533, 2013). "Obese and insulin-resistant men with higher insulin levels would be expected to have lower SHBG levels and consequently lower total testosterone concentrations." (PMID 24391852, 2013). "Our first observation in this study was an early stage of insulin resistance in women with pGDM manifested by higher levels of fasting insulin, and HOMA IR compared to control group." (PMID 23819960, 2013). "Homeostasis model assessment of insulin resistance (HOMA-IR) as a surrogate marker of insulin resistance based on measurement of fasting plasma glucose and insulin, has been widely used in clinical practice." (PMID 23825975, 2013). "Homeostasis model assessment of insulin resistance index and serum insulin levels were used to evaluate insulin resistance." (PMID 23894289, 2013). "In our study fasting insulin was applied as a surrogate marker of insulin resistance leading to different combinations of fasting insulin and the glucose concentration such as HOMA-IR." (PMID 24086723, 2013). "This was assessed by detecting the changes in interrupted glucose metabolism via estimation of serum glucose, insulin, the adipocytokine “adiponectin,” homeostasis model assessment of insulin resistance (HOMA-IR) index, and lipid profile." (PMID 24106697, 2013). "Whole-body insulin resistance usually results from decreased insulin sensitivity in skeletal muscle because it is the main tissue responsible for insulin-stimulated glucose uptake." (PMID 23997935, 2013). "In one trial (which was non-randomised) there was evidence of a favourable effect on fasting insulin and insulin resistance as estimated using the HOMA model." (PMID 24349496, 2013). "Clinical manifestation of T2D is characterised by insulin resistance, impaired insulin secretion and pancreatic beta cell dysfunction." (PMID 24324833, 2013). "High-fat diets, in particular high saturated fatty acid (SFA) diets, have been shown to exert detrimental effects on adiposity, inflammation and insulin sensitivity, promoting the development of insulin resistance, the MetS and T2DM." (PMID 23306188, 2013). "This has been viewed as presumptive evidence that insulin secretion plays a more important etiologic role in T2D than insulin resistance." (PMID 23997649, 2013). "The authors reported significant decreases in fasting insulin levels (−28.3%) and homeostasis model assessment of insulin resistance (HOMA-IR, −29.8%) in the exercise training group as compared to the controls after the intervention." (PMID 24454364, 2013). "Nr4a3 expression is reduced in skeletal muscle and adipose tissue in multiple rodent models of insulin resistance, while increased expression of Nr4a3 increases insulin responsiveness and GLUT4 translocation." (PMID 23349861, 2013). "The strength of the present study is the demonstration that the small intestine of insulin resistant humans and mice secrete a protein factor/s inducing insulin resistance by impairing the insulin signaling." (PMID 23437106, 2013). "An estimate of insulin resistance by homeostasis model assessment (HOMA-IR index) was calculated from fasting insulin and glucose." (PMID 23578341, 2013). "In response to the development of insulin resistance, the specialized cells that are devoted to insulin production (ie, the β-cells in the pancreatic islets) react by increasing their cell mass and amount of insulin secretion." (PMID 24176906, 2013).
Insulin resistance (continued). "Associations between normal weight obesity defined as high percent body fata with metabolic syndrome and insulin resistance, insulin sensitivity and β cell function, 1978/79 Ribeirão Preto birth cohort." (PMID 23556000, 2013). "Since obese condition results in increased adipose tissue lipolysis leading to increased plasma FFA, lipotoxicity that accumulation of bioactive lipid intermediates inhibits insulin response has gained credibility for development of insulin resistance." (PMID 23761785, 2013). "The animal is moderately obese, and both impaired insulin response to glucose and insulin resistance contribute to diabetes." (PMID 23671880, 2013). "Insulin resistance and impaired insulin secretion are the main physiological abnormalities associated with T2DM." (PMID 24453844, 2013). "An increase in the HOMA index value of >2.89 is accompanied both by an increase in insulin secretion and by an increase in insulin requirement, which suggests inefficient secretion in response to insulin resistance." (PMID 23819910, 2013). "Conventional understanding would suggest that increased insulin resistance in patients with higher BMI necessitates higher insulin per kilogram dosing." (PMID 24499517, 2013). "One interesting potential role for these miRNAs is to increase insulin resistance in ruminants by targeting insulin signalling." (PMID 24020371, 2013). "A positive correlation was found between baseline insulin levels and C3 levels, and serum C3 has been considered as an inflammatory marker of insulin resistance." (PMID 23509804, 2013). "This was accompanied by significantly increased glucose, insulin and glucagon levels and the related gene expressions, all of which indicated possible insulin resistance." (PMID 24349075, 2013). "We also observed that this SNP was associated with not only T2DM and hyperglycemia but also the other metabolic features such as waist circumference, fasting serum insulin level and insulin resistance." (PMID 23431394, 2013). "Adiponectin increases insulin sensitivity by several mechanisms, and these results are thus consistent with previous results regarding insulin resistance." (PMID 23894285, 2013). "Recent studies have implicated saturated fatty acid-induced hyperactivity of PP2A in the pathogenesis of insulin resistance, at the level of Akt activation, in all major insulin responsive cell types." (PMID 24150286, 2013). "Metformin is an insulin sensitising agent which is known to improve vascular health outcomes in type 2 diabetes (T2D) and other individuals with insulin resistance." (PMID 23865839, 2013). "Insulin resistance induces muscle wasting through complex mechanisms, including insulin/IGF-1 and PI3K/Akt signaling pathways." (PMID 24382946, 2013). "Type 2 diabetes is a metabolic syndrome characterized by insulin resistance and decreased in insulin secretion." (PMID 23819126, 2013). "The improvement of insulin sensitivity by SIRT1 has implications in the treatment of insulin resistance and type 2 diabetes." (PMID 23442260, 2013). "A study reported that high circulating levels of serum RBP4 increased the potential for insulin resistance by blocking insulin signaling in muscle, thus increasing hepatic glucose output." (PMID 24282409, 2013). "Both clinical and experimental studies have shown that changes in the abundance of insulin signalling molecules in skeletal muscle and adipose tissue precede the development of insulin resistance and type 2 diabetes mellitus (T2DM)." (PMID 24386400, 2013). "Both LP and BB extracts blocked the body weight gain, lowered fasting blood glucose, serum TC, liver lipid levels, and improved glucose tolerance and insulin resistance, and lowered serum insulin levels in HF diet-fed mice." (PMID 24147098, 2013).
Insulin resistance (continued). "One year later, girls in the high BPA exposure group showed higher levels of androstenedione, testosterone, estradiol, and insulin, and homeostasis model assessment of insulin resistance (HOMA-IR) index, than those in the other groups (p < 0.05)." (PMID 24189184, 2013). "These formulas are most similar to the biological phenomenon for insulin resistance and their reproducibility solely depends on the fasting levels of glucose and insulin used to calculate their values." (PMID 23409091, 2013). "Pubertal insulin resistance was accompanied by greater fasting serum insulin concentrations while serum glucose concentrations were unchanged." (PMID 23383164, 2013). "In NAFLD, hepatic insulin resistance mediates the failure of the insulin-signaling pathway, leading to molecular and cellular changes that result in excess accumulation of triglycerides in the hepatocytes." (PMID 24072087, 2013). "In summary, insulin resistance describes a physiological condition which is characterized by reduced tissue responses to the action of insulin for any given blood concentration of the hormone." (PMID 23431467, 2013). "Correlation between the fasting plasma levels of lipid oxidation stress markers and glycometabolism markers, insulin secretion, and insulin resistance during OGTT." (PMID 23691063, 2013). "Because there were no changes in insulin levels, omega-3 fatty acid depletion promoted insulin resistance by an insulin independent pathway." (PMID 23896654, 2013). "Homeostasis model assessment for insulin resistance (Homa-IR), insulin acuity index (IAI), β-cell function index (Homa-BCF) as well as secretion index (IS) were determined." (PMID 24353633, 2013). "The HOMA-IR result in the low dose E. guineensis group points to an increase in insulin sensitivity and reduction in insulin resistance as potential mechanisms of action." (PMID 23547788, 2013). "With insulin resistance, cells fail to respond to insulin to metabolize glucose, triggering a further surge of insulin." (PMID 24391586, 2013). "Insulin secretion in general rises since the very beginning of the appearance of the condition of insulin resistance, aiming for compensation of reduced action to insulin." (PMID 24146977, 2013). "Given that women with prior GDM have innate tendencies towards insulin resistance, one would expect our study population to have higher fasting insulin levels." (PMID 23705645, 2013). "The insulin-induced increase of microvascular endothelium-dependent vasodilation is abolished in insulin resistance conditions such as obesity." (PMID 23573411, 2013). "Insulin resistance can be assessed by measuring insulin level at fasting or assessing the peak level of insulin achieved after oral glucose tolerance test (OGTT)." (PMID 23424687, 2013). "Insulin resistance (IR), defined as decreased sensitivity and/or responsiveness to metabolic actions of insulin that promote glucose disposal, is one of the important CVFs." (PMID 24391852, 2013). "Palmitic acid (PA) was chosen as a stimulant to induce ROS production in endothelial cells and successfully established insulin resistance evidenced by the specific impairment of insulin PI3K signaling." (PMID 23840461, 2013). "The two major types are type 1 and type 2 which are characterised by impaired insulin production or insulin resistance, respectively." (PMID 24340000, 2013). "T2DM is a common metabolic disorder characterized by chronic hyperglycemia and dyslipidemia resulting from peripheral tissue insulin resistance and impaired insulin secretion from the pancreas." (PMID 23690865, 2013). "Since memory deficits are positively correlated with increases in insulin resistance, this suggests that insulin signals neurons directly in the brain." (PMID 23924506, 2013).
Insulin resistance (continued). "Insulin resistance (IR) is defined clinically as the inability of a known quantity of exogenous or endogenous insulin to increase glucose uptake and utilization in an individual as much as it does in a normal population." (PMID 24353584, 2013). "In humans, an increase in serum PEDF is associated with the development of insulin resistance, and a reduction in serum PEDF is associated with improved insulin sensitivity following weight loss." (PMID 24367624, 2013). "In overt or subclinical hypothyroidism, insulin resistance leads to glucose-stimulated insulin secretion." (PMID 23671867, 2013). "Many studies suggest that adiponectin is an important regulator of insulin sensitivity and glucose homeostasis, with several reports confirming an inverse relationship between insulin resistance and plasma adiponectin levels." (PMID 23691290, 2013). "Recently, a randomized study in 15 insulin resistant subjects has shown that 8 weeks of resistant starch supplementation (40 g/day) improved insulin resistance and subsequently FFA metabolism." (PMID 23584084, 2013). "This highlights the mechanisms behind partial insulin resistance or postreceptor selective defect in signaling through one arm of the insulin signaling pathway evident in common obesity-related insulin resistance." (PMID 23766565, 2013). "Several metabolic and signaling pathways are involved in perpetrating the disturbances of obesity and insulin resistance in the three main insulin-sensitive tissues." (PMID 23781256, 2013). "Several studies indicate a role for SMs in the development of T2D by influencing insulin resistance as well as insulin secretion." (PMID 24205231, 2013). "Cumulatively, we find that GWAS genes relate directly to insulin secretion and indirectly, through collaborating with other genes, to insulin resistance." (PMID 23308243, 2013). "Subsequent analysis did not detect any association of rs4929949 to phenotypic measurements describing body adiposity or to metabolic factors such as insulin levels, triglycerides and insulin resistance (HOMA)." (PMID 23967198, 2013). "Several effects such as insulin resistance, elevation of serum insulin, hepatic lipid accumulation, oxidative stress, and abnormal mitochondria have been reported." (PMID 27335818, 2013). "The marked increases in the amount of exogenous insulin requirement to maintain euglycemia as well as circulating insulin levels during CPB surgery suggest the development of insulin resistance." (PMID 23840093, 2013). "The role of low pH and cellular oxidative stress on the function of pancreas, insulin action, and metabolism in DKA and MI and the clinical significance of insulin autoantibodies in the development of insulin resistance require further study." (PMID 23424687, 2013). "Homeostasis model assessment (HOMA) of insulin resistance (HOMA-IR) demonstrated that insulin sensitivity was improved post-treatment." (PMID 23837842, 2013). "Insulin resistance was estimated by measuring the Quantitative Insulin Sensitivity Check Index (QUICKI), using a cut-off value of 0.33." (PMID 23351215, 2013). "Reduced β-cell insulin response, in the setting of insulin resistance, is also seen among Asians outside pregnancy." (PMID 23467680, 2013). "Previous studies demonstrated the rapid development of insulin resistance in skeletal muscle following T-HS, with the earliest insulin signaling defect occurring at 60 minutes." (PMID 24204984, 2013). "The increased insulin resistance was characterized by increased insulin secretion (ANOVA effect of diet p<0.001) needed to maintain glucose levels similar to baseline levels (ANOVA effect of diet p = 0.054)." (PMID 24023709, 2013). "The current assessment of insulin resistance (IR) in epidemiology studies relies on the blood measurement of C-peptide or insulin." (PMID 24353253, 2013).
Insulin resistance (continued). "Exercise has been demonstrated to improve fitness, insulin requirement, lipids, insulin resistance and well- being, and to reduce cardiovascular disease and mortality in people with long standing type 1 diabetes." (PMID 23777480, 2013). "Each 1-SD increase of eosinophil percentage was in relation to a 34% decrease of elevated fasting serum insulin (OR 0.66 [95% CI 0.47–0.92]; P = 0.01) and a 37% decrease of insulin resistance (OR 0.63 [95% CI 0.45–0.87]; P = 0.005), respectively in NGT." (PMID 23894289, 2013). "The most common clinical manifestations of type 2 DM is insulin resistance, which mostly occurs in skeletal muscle, and the impairment of insulin secretion." (PMID 24112518, 2013). "Administration of recombinant resistin in rodents impaired hepatic insulin sensitivity and glucose metabolism, and treatment with anti-resistin anti-sense oligonucleotides reversed hepatic insulin resistance." (PMID 23484124, 2013). "Insulin resistant cases and controls have been further stratified in four subgroups according to fasting plasma glucose and insulin values." (PMID 23497533, 2013). "We have shown DHEA to stimulate basal glucose uptake, mimicking the action of insulin, consistent with the amelioration of hyperglycemia and insulin resistance observed upon DHEA treatment in vivo." (PMID 24022868, 2013). "This is the first study raising the possibility that higher insulin levels and/or insulin resistance are directly responsible for lower vitamin D levels, but we do not have our own data to explain this result, and this is the limitation of this study." (PMID 23509804, 2013). "Other physiological factors were not included such as adiponectin, which is regulated by GC and relates to insulin resistance by augmenting insulin sensitivity in various target tissues." (PMID 24312573, 2013). "In another study, borapetoside C increased glucose utilization, delayed the development of insulin resistance, and enhanced insulin sensitivity in diabetic mice." (PMID 24319481, 2013). "Cross-sectional associations between 25(OH)D and FPG, fasting plasma insulin (FPI) and homeostatic model assessment-insulin resistance (HOMA-IR), a marker of insulin resistance, were estimated from multiple regression analyses." (PMID 22729969, 2013). "There is similar evidence of a reversal from insulin sensitivity to insulin resistance in the lamb following IUGR induced by restriction of placental growth and function (PR)." (PMID 23424667, 2013). "Intramyocellular DAG accumulation has been associated with insulin resistance, as DAG modulates intracellular insulin signaling and action, thereby decreasing insulin sensitivity." (PMID 24023810, 2013). "In obese patients, excessive insulin is secreted to inhibit hyperglycemia due to insulin resistance; however, insulin itself promotes the growth of cancer cells through stimulation of the activity of insulin-like growth factor-1 (IGF-1)." (PMID 23291663, 2013). "Insulin reduces islet glucotoxicity and has a paradoxical effect on improving insulin sensitivity in the context of insulin resistance." (PMID 24260037, 2013). "To evaluate the effect of EE on impaired glucose uptake in an insulin-resistant state, we induced insulin resistance using TNF-α treatment in 3T3-L1 adipocytes and measured the effect of EE on TNF-α-mediated suppression of glucose uptake." (PMID 23690865, 2013). "Insulin resistance is a condition in which a given concentration of insulin produces a less than expected biological effect." (PMID 24353584, 2013). "In recent research, reduced insulin sensitivity and increased insulin resistance was found after short term sleep restriction." (PMID 23383010, 2013). "It is known that normal insulin secretion in pancreatic ß-cells depends on vitamin D. A reduction in vitamin D level can result in an increase in insulin resistance and reduction in insulin secretion." (PMID 23631804, 2013).